MYCN (MYCN proto-oncogene, bHLH transcription factor)
Diseases named in the same sentence as MYCN in open-access papers (continued):
Sharing a sentence is not in itself a finding about the gene and the disease.
glioma (57 papers, 1994 to 2025). A benign or malignant brain and spinal cord tumor that arises from glial cells (astrocytes, oligodendrocytes, ependymal cells). "Whole-exosome sequencing has revealed a consistent co-amplification of ID2, a gene implicated in glioma tumorigenesis, suggesting a potential interplay between MYCN and ID2." (PMID 40365336, 2025). "One model, generated by transduction of NSCs with a mutationally stabilized MYCN and transplantation of respective cells into nude mice, generated forebrain tumors with features of glioma." (PMID 38001143, 2023). "The proportion of CD8 T-cells, another prominent immune cell type in high-grade gliomas, was associated with oncogene amplifications in MYCN, PDGFRA, and MDM2." (PMID 34496929, 2021). "Seven cases were found to have MYCN amplification in the course of routine mutational profiling of 552 patients with central nervous system tumors between December 2016 and July of 2019 and an eighth patient was identified from an unrelated set of cases." (PMID 32641156, 2020). "The MYCN amplification status may be used to categorize another subtype of glioma in addition to H3 or IDH1 mutations." (PMID 39802403, 2025). "Due to MYCN plays a key role in cell proliferation and cell growth during embryonic development and it is often associated with a number of childhood-onset tumors, here we combined Brain Lower Grade Glioma to show the results of analysis." (PMID 33968733, 2021). "CNS_156, classified as a diffuse paediatric‐type high‐grade glioma, MYCN subtype, had focal MYCN amplification." (PMID 41033792, 2025). "HGSC showed among the highest expression of MYCN, third only to low-grade glioma and uterine carcinosarcoma." (PMID 38748789, 2024). "The differential diagnosis with H3K27-altered gliomas is especially relevant in MYCN cases, as these tumours can be found in the brainstem." (PMID 39126064, 2024). "Some studies have reported MYCN amplification in gliomas harboring wild-type IDH arising in pediatric LFS cases." (PMID 38605367, 2024). "As mentioned in the Introduction, PDGFRA and MYCN amplifications were characteristic of some pediatric H3-wildtype high-grade gliomas." (PMID 38201659, 2024). "These murine tumors show a similar histology and marker expression as human tumors of the methylation class “pediatric high-grade glioma MYCN”." (PMID 38001143, 2023). "We also observed regional heterogeneity in genes associated with poor clinical prognosis in IDH-mutant glioma, including CDKN2A/B, CDK4, MYC, MYCN, and PDGFRA23." (PMID 37770427, 2023). "Meanwhile, referring to the biological properties of MYCN (Supplement 2), we selected Brain Lower Grade Glioma to validating indispensable genes." (PMID 33968733, 2021). "IC-2664PNET was derived from a patient diagnosed with a primitive neuroectodermal tumor (PNET) but was further molecularly classified as a MYCN-subtype high-grade glioma." (PMID 31693904, 2019). "As a result, the expression of MYCN was significantly over-expressed with the ascending order of glioma grade, accompanying the down-regulation of miR-29b." (PMID 28423357, 2017). "As a conclusion, miR-29b inhibits the growth of glioma via MYCN dependent way and can be a biomarker for the diagnosis of glioma." (PMID 28423357, 2017). "Collectively, our results demonstrate that overexpression of Survivin increases tumorigenicity of mycN-transduced U251-MG glioma cells by combined induction of CIN and prevention of apoptosis." (PMID 29282022, 2017). "In this study, we further validated the decreased level of miR-29b in glioma tissues and demonstrated its functional roles in inhibiting the growth of glioma via MYCN dependent way." (PMID 28423357, 2017).
glioma (continued). "We also detected the expression of MYCN in glioma tissues, and found that the expression of miR-29b was negatively correlated with the mRNA and protein levels of MYCN." (PMID 28423357, 2017). "Then, luciferase reporters assay created as pGL3-MYCN-WT-3′UTR and pGL3 -MYCN-MT -3′UTR revealed that miR-29b directly regulated MYCN expression via binding 3′UTR of MYCN in glioma cells." (PMID 28423357, 2017). "Taken together, our data shows that overexpression of Survivin increases mycN-induced tumorigenicity of U251-MG glioma cells probably by combined induction of CIN and prevention of apoptosis." (PMID 29282022, 2017). "The target of miR-29b was predicted using miRanda, TargetScan and PicTar sofeware and we also found MYCN was a direct target of miR-29b in glioma cells and miR-29b inhibited the proliferation of glioma cells via MYCN dependent way." (PMID 28423357, 2017). "About the biological functions of miR-184, studies have linked its overexpression to squamous cell carcinoma of the tongue, its downexpression to gliomas and MYCN-amplified neuoblastoma." (PMID 22017809, 2011). "Three significant pathways were identified–FGFR3 signaling in chondrocyte proliferation and terminal differentiation, nanoparticle-mediated activation of receptor signaling, and MYCN to transcriptional activation–each of which shows mechanistic or therapeutic relevance to IDH-wildtype gliomas." (PMID 41356219, 2025). "One postulated mechanism for MYCN enrichment relies on FBXW7 deletion (located in chromosome 4q31.3; 4q loss is found in 70% of H3G34-altered gliomas), which is a component of the SCF-like ubiquitin ligase complex that targets MYC/MYCN for proteasomal degradation." (PMID 39126064, 2024). "Since H3- and IDH-wildtype diffuse high-grade gliomas, MYCN subtype, may occur in midline structures, FISH for MYCN rearrangements would be recommended." (PMID 39126064, 2024). "While partial Arf suppression causes increased malignancy in MYCN-expressing tumors, complete Arf depletion promotes photoreceptor-negative high-grade glioma formation." (PMID 36869047, 2023). "Paediatric high-grade gliomas with MYCN amplification (HGG-MYCN) are rare and highly aggressive." (PMID 38001143, 2023). "Although there are no direct association between three other genes and MYCN in existing studies, from the co-expression of Brain Lower Grade Glioma, it is possible that had correlation between them." (PMID 33968733, 2021). "Co-expression correlation between indispensable genes and MYCN of Brain Lower Grade Glioma." (PMID 33968733, 2021). "It was also evident that MYCN could promote the formation of glioma from GFAP-positive stem cells isolated from the forebrain ventricular zone (VZ)." (PMID 28333115, 2017). "Consequently, we found that MYCN, a gene that has been reported as a significant regulator in the development and progression of glioma, was a candidate target of miR-29b." (PMID 28423357, 2017). "Screens including either grade II and grade III gliomas or pediatric HGGs have demonstrated amplifications of both c-MYC as well as MYCN, and in the context of pediatric HGG a clear association of MYCN amplifications with anaplastic astrocytomas was reported." (PMID 28333115, 2017). "Based on such methods, we found an important gene involved in glioma, MYCN, could be a key target of miR-29b in the development and progression of glioma." (PMID 28423357, 2017).
glioma (continued). "In the present study, we for the first time verified the abnormally down regulation of miR-29b in glioma with large number of clinical samples, and we found miR-29b may act as a tumor inhibitor via MYCN dependent pathway." (PMID 28423357, 2017). "We additionally predicted the targets of miR-29b with miRanda, TargetScan and PicTar, and finally we found MYCN, a previously reported tumor promoter in glioma carcinogenesis, shared the same seed complementarity to MYCN 3′ UTR, which was further validated by luciferase report assay." (PMID 28423357, 2017). "MYCN gliomas may also have an embryonal PNET-like histology." (PMID 39126064, 2024). "We detected genes upregulated in PBT030 cells, such as SOX2, MYCN, NOS2, RUNX2, and VEGFA, while PBT147 cells upregulated level of PTEN, STAT6, CA9 and TLR2, demonstrating differences among PBT cell lines, which can be explained by various driving mutations and heterogeneity in glioma lines." (PMID 38449858, 2024). "In addition, some subtypes of pediatric and young adult high‐grade gliomas, including those with MN1 alterations, MYCN amplifications, and H3‐3A G34 mutations, may be histologically indistinguishable from CNS embryonal tumors." (PMID 35763016, 2022). "Moreover, we detected the expression of MYCN in normal brain tissues and glioma tissues." (PMID 28423357, 2017). "Diffuse paediatric-type high-grade gliomas, H3-wildtype and IDH-wildtype can be further subclassified into three subtypes: RTK1 (Receptor of Tyrosine Kinase-1), RTK2, and MYCN, each with typical molecular alterations." (PMID 39126064, 2024). "One clearly distinguishable class of these tumors are “pediatric high-grade gliomas with MYCN amplification”, hereafter called “HGG-MYCN”." (PMID 38001143, 2023). "In malignant glioma with primitive neuroectodermal components (MG-PNET), a rare type of brain tumor that most likely develops from already existing glioma, about half of the patients demonstrate mutually exclusive MYC or MYCN amplifications." (PMID 33585252, 2020). "Expression of MYCN correlated with that of SGO1/SGO2, except in lower-grade gliomas, and SGO1/SGO2 expression tended to be higher in some MYC-overexpressing cancers." (PMID 27539729, 2016). "Finally, the MYCN transcriptional activation pathway reflects MYCN-driven oncogenic transcriptional programs, which define an aggressive subset of IDH-wildtype gliomas characterized by high proliferation, metabolic reprogramming, and poor prognosis." (PMID 41356219, 2025). "Diffuse pediatric-type high-grade glioma, H3-wildtype and IDH-wildtype can further be divided into 3 subtypes: diffuse pediatric-type high-grade glioma RTK2, diffuse pediatric-type high-grade glioma RTK1, and diffuse pediatric-type high-grade glioma MYCN." (PMID 37214395, 2023). "Although a few mouse tumor models driven by alterations of MYCN have been described, none of them have developed gliomas with similarities to human HGG-MYCN." (PMID 38001143, 2023). "Likewise, miR-146b, miR-124a, and miR-34a were introduced into glioma cells from transfected hBMSC-derived EVs and abrogated glioma growth by decreasing EGFR and NF-κB protein, silencing FOXA2 and downregulating MYCN, respectively." (PMID 34479611, 2021). "This includes a case of angiomatoid fibrous histiocytoma with EWSR1-CREM fusion, an angiocentric glioma with MYB-QKI fusion, a glioma with MYCN amplification, two patients with non-canonical IDH mutations (both with IDH1 R132S), and a patient with a KRAS mutation." (PMID 38764578, 2024). "Genomically, the tumor is H3 K27/G34 wild-type and shows no alterations in MYCN, MYC, or tyrosine kinase receptors, which are commonly seen in pediatric high-grade gliomas." (PMID 41323387, 2025).
rhabdomyosarcoma (48 papers, 2009 to 2025). A rare aggressive malignant mesenchymal neoplasm arising from skeletal muscle. "Furthermore, MYCN amplification and single nucleotide variants have been identified in various other tumors, encompassing Wilms’ tumor, rhabdomyosarcomas, and lung cancers." (PMID 38884091, 2024). "GEO accession number for publicly available ChIP-seq data of MYCN, and histone marks derived from rhabdomyosarcoma cell line RH4 is GSE83728." (PMID 37781575, 2023). "In alveolar rhabdomyosarcoma, amplification of MYCN is present in 25% of cases and overexpression of MYCN occurs in 55% of cases." (PMID 33628735, 2020). "The inhibition of cell growth by inhibiting MYCN shows promising therapeutic potential for rhabdomyosarcoma as well as other MYCN-amplified cancers." (PMID 28358317, 2017). "Recently, Anderson and colleagues have provided further evidence that MYCN mRNA is virtually undetectable in most adult human tissues, at variance with rhabdomyosarcoma and NB cell lines that over-express this oncogene." (PMID 23162796, 2012). "All cell lines apart from DND-41 showed high MYCN transcript and protein expression, at levels comparable to other cell lines known to overexpress MYCN (CCA rhabdomyosarcoma cell line) although lower than MYCN-amplified cell lines (RH30 rhabdomyosarcoma cell line)." (PMID 24334727, 2014). "To investigate whether the mechanism by which MYCN regulates gene expression in NB is consistent in other embryonal tumors with MYCN overexpression, we interrogated publicly available ChIP-seq data from rhabdomyosarcoma (RMS) cell line RH4 that expresses high levels of MYCN (GSE83728)." (PMID 38547242, 2024). "To investigate whether the mechanism by which MYCN regulates gene expression in NB is consistent in other embryonal tumor marked by MYCN overexpression, we interrogated publicly available ChIP-seq data from rhabdomyosarcoma (RMS) cell line RH4 that expresses high levels of MYCN (GSE83728)." (PMID 37781575, 2023). "The minimum common region of amplification at 2p24 in rhabdomyosarcoma (RMS) and NB has been found to consistently include the oncogene MYCN and amplification of MYCN is used clinically as a prognostic marker in NB." (PMID 29466962, 2018). "Moreover, in PAX3-FOXO1-driven rhabdomyosarcoma, the fusion protein exploits super-enhancers to set up a CRC machinery in collaboration with the master TFs (MYOG, MYOD and MYCN); this CRC is addicted by rhabdomyosarcoma cells for survival and proliferation." (PMID 33080033, 2020). "MYCN-amplification is not the only critical event for aberrant cell growth of rhabdomyosarcoma, as copy number can influence cell growth." (PMID 28358317, 2017). "NB cell lines derived from high-stage, aggressive tumors as well as the rhabdomyosarcoma cell line RH-41 all presented with high cdk1/CCNB1 expression independent of the MYCN amplification status." (PMID 26029996, 2015). "Notably, MYCN's unique expression profile, predominantly absent in mature tissues but frequently dysregulated in a substantial portion of alveolar rhabdomyosarcoma cases, makes it an enticing target for immunotherapeutic interventions." (PMID 39802403, 2025). "In alveolar rhabdomyosarcoma, the chimeric transcription factor PAX3-FOXO1 interacts with the master transcription factors MYCN, MYOG and BRD4 at target gene super-enhancers, resulting in over-expression of SOX8, MYOD1, MYOG and MYCN, alveolar rhabdomyosarcoma tumorigenesis and dependence on BRD4." (PMID 38135679, 2023).
small cell lung carcinoma (46 papers, 2009 to 2025). Small cell lung cancer (SCLC) is a highly aggressive malignant neoplasm, accounting for 10-15% of lung cancer cases, characterized byrapid growth, and early metastasis. "Whole lysate from small cell lung cancer H69 cells was added as a positive control for MYCN expression." (PMID 35408939, 2022). "In adult cancers, amplification of MYCN is present in 40% of neuroendocrine prostate cancers and 5% of prostate adenocarcinomas, 15%-20% of small-cell lung cancers and 17.5% of basal cell carcinomas." (PMID 33628735, 2020). "The KIM MYCN amplification curated gene sets identify the gene sets upregulated and downregulated by MYCN amplification in small cell lung cancer cell lines." (PMID 29515779, 2018). "For example, amplification of MYCL or the presence of the RLF-MYCL1 fusion gene are mutually exclusive of amplifications of MYC or MYCN in small cell lung cancer." (PMID 29028833, 2017). "In addition, USP7 inhibition was reported to restore chemosensitivity in MYCN-overexpressing small-cell lung cancer models." (PMID 37762082, 2023). "The L-MYC gene was initially discovered in small-cell lung cancer based on homology to both c-MYC and MYCN." (PMID 37046804, 2023). "Depletion of EZH2 led to N-Myc polyubiquitination by SCF-FBXW7, and subsequent N-Myc degradation reduced tumor cell growth in MYCN-amplified NB and small cell lung carcinoma cells." (PMID 37762082, 2023). "MYCN is most frequently overexpressed in cancers of neural origin and also regulates genes functioning in ribogenesis, whereas MYCL is most often overexpressed in small cell lung carcinomas." (PMID 38225354, 2024). "MYCN opposite-strand (MYCNOS, N-CYM, MYCN-AS1, NYCM, CYMN) is produced by antisense transcription across exon 1 and intron 1 of MYCN that has been shown to be highly expressed in MYCN-amplified NB and small cell lung cancer." (PMID 29466962, 2018).